NGF (nerve growth factor)
Diseases named in the same sentence as NGF in open-access papers (continued):
Sharing a sentence is not in itself a finding about the gene and the disease.
breast cancer (continued). "Nevertheless, similar findings from other oncological fields support the relevance of this issue, as for example in breast cancer the formation of NGF and NTRK1 autocrine axis was evidenced as well." (PMID 29904026, 2018). "NGF is involved in the proliferation of breast cancer cells through the NGFR TrkA-MAPK pathway and it prevents apoptosis by activating the NGFR p75NTR-NFκB pathway." (PMID 28679437, 2017). "NGF is reported to participate in neuronal cell survival and differentiation and there are growing evidences of role of NGF as major stimulator of breast cancer cell growth." (PMID 28415766, 2017). "In line with our results, the expression patterns of NGF and HO1 were associated with advanced clinicopathologic factors of breast carcinomas, and were independent indicators of poor prognosis of breast carcinoma patients." (PMID 28679437, 2017). "Sortilin complexed with TrkA, another tyrosine kinase receptor for NGF, was also identified in breast cancer, promoting cell invasion through pro-NGF binding to this complex." (PMID 27120782, 2016). "MDA-MB-231 breast cancer cells overexpressing HA-TrkA were used to examine the signaling pathways involved in NGF response." (PMID 25840418, 2015). "Concerning breast cancer, it has been shown that NGF promotes both tumour cell survival and proliferation." (PMID 25069766, 2014). "A deregulation in NGF signaling has been shown to promote proliferation, migration, angiogenesis and metastasis in different cancers, including breast cancer, melanoma and pancreatic cancer." (PMID 25296882, 2014). "The gene expression and protein expression of IGF-1R, PDGFA, NGF, NF-κB and JNk-2 in breast cancer cells was inhibited by UTI and TXT." (PMID 22217202, 2012). "UTI and TXT down-regulate the expression of mRNA and protein of IGF-1R, PDGFA, NGF, NF-κB, and JNk-2 in breast cancer cells and xenografted breast tumors." (PMID 22217202, 2012). "In the present experiment, we find that UTI and TXT inhibit gene and protein expression of IGF-1R, PDGFA, NGF, NF-κB, and JNk-2 in breast carcinoma cells and the effect of UTI+TXT is strongest." (PMID 22217202, 2012). "UTI, TXT, and UTI+TXT also significantly inhibit the NGF mRNA expression on MDA-MB-231 breast carcinoma cells compared with the control group (P < 0.05)." (PMID 22217202, 2012). "NGF is a pluripotent polypeptide growth factor, strong mitogen related to the proliferation, invasion, and vascularization of breast carcinoma cells." (PMID 22217202, 2012). "In contrast to mitogenic signaling, NGF pro-survival effects in breast cancer cells are mediated by the p75NTR receptor." (PMID 24212627, 2011). "In a xenograft model of breast cancer, antibodies against NGF were successful in reducing tumor growth." (PMID 24212627, 2011). "For example, in breast cancer the aberrant expression of nerve growth factor stimulates proliferative signaling through TrkA and pro-survival signaling through p75NTR." (PMID 24212627, 2011). "Since NGF is expressed in 80% of breast cancers, this suggests that NGF signaling has a potentially broader target range than current therapies, which are directed against either estrogen signaling or HER2." (PMID 24212627, 2011). "In breast cancer cells, a novel adaptor Bex2 has recently been shown to be required for NGF/p75NTR-dependent NF-κB activation and prosurvival effects." (PMID 24212627, 2011). "Breast cancer and prostate cancer are notable because there is a large body of evidence demonstrating how NGF in particular is involved in disease development and progression." (PMID 24212627, 2011). "NGF exerts pro-survival effects on a wide range of breast cancer cell lines (MCF-7, MDA-MB-231, T-47D and BT-20) and can protect them from C2-ceramide induced apoptosis." (PMID 24212627, 2011). "Recently, TrkA signaling was also shown to play a role in breast cancer metastasis and angiogenesis, which expands the role of NGF signaling in this disease." (PMID 24212627, 2011).
breast cancer (continued). "Increased Brn-3b expression via growth factors such as NGF and EGF or the hormone, estradiol, which are implicated in enhancing the growth of breast cancer cells, are likely to be are propagated by autoregulation." (PMID 21241485, 2011). "For example, immunohistochemical analysis has shown that NGF is expressed in up to 80% of breast cancer tumor biopsies." (PMID 24212627, 2011). "In breast cancers, we have previously shown that NGF and its tyrosine kinase receptor TrkA are overexpressed compared to normal breast tissues." (PMID 20569463, 2010). "To determine the potential effect of NGF in breast cancer angiogenesis, we first performed Matrigel plug assay in SCID mice." (PMID 20569463, 2010). "The presence of a neutralizing antibody anti-NGF in the Matrigel plugs decreased about two third the quantity of hemoglobin and microvessel density, suggesting that NGF is strongly involved in breast cancer angiogenesis." (PMID 20569463, 2010). "We showed that both recombinant NGF and NGF produced by breast cancer cells stimulated angiogenesis in Matrigel plugs in immunodeficient mice." (PMID 20569463, 2010). "Here, we present in vivo and in vitro data that give new insights into mechanisms of the involvement of NGF in breast cancer angiogenesis." (PMID 20569463, 2010). "As VEGF is considered as one of the most efficient proangiogenic factors in breast cancer angiogenesis, and as NGF is found to be overexpressed in breast cancer, our present findings highlight the importance of NGF as a proangiogenic factor in breast cancer." (PMID 20569463, 2010). "In the present study all resulting mammary tumors expressed mRNA for the neurotrophins NGF and BDNF and neurotrophin receptors TrkA, TrkB and p75NTR." (PMID 19173004, 2009). "Additionally, NGF was found to be involved in the activation of the PI3K/AKT signaling pathway in breast cancer 34, which was consistent with our enrichment analysis results." (PMID 40612670, 2025). "Additionally, ECM stiffness alters the secretory profile of breast cancer cells, increasing nerve growth factor (NGF) expression, further facilitating interactions between cancer cells and nerve structures, ultimately promoting PNI." (PMID 40563551, 2025). "NGF is upregulated in the tumor microenvironment of breast cancer." (PMID 38375479, 2024). "In xenograft mouse models of TNBC, treatment with anthracycline was evidenced to increase sympathetic nerve fiber activity and norepinephrine concentration in mammary tumors through the induction of nerve growth factor (NGF) by tumor cells, thus driving metastasis." (PMID 38802766, 2024). "Nerve growth factor is a potential therapeutic target in breast cancer." (PMID 39346791, 2024). "This aspect may be attributed to the role of nerve growth factor in the proliferation, invasion, and metastasis of breast cancer cells, especially in TNBC62–64." (PMID 38310106, 2024). "Nerve growth factor (NGF), the prototypic neurotrophin, could be targeted in breast cancer to inhibit tumor cell proliferation, survival, and metastasis." (PMID 39346791, 2024). "Intriguingly, it was reported that tamoxifen, prescribed to breast cancer patients, may inhibit TrkANGF phosphorylation and, respectively, the NGF-elicited proliferation of epithelial cells from breast cancer." (PMID 39065809, 2024). "Moreover, NGF promotes the secretion of VEGF by breast cancer cells, and the angiogenic capacity of NGF is inhibited by in vivo administration of anti-VEGF antibodies." (PMID 38375479, 2024). "Furthermore, BEX2 overexpression enhances the antiproliferative effect of tamoxifen, suggesting the involvement of the NGF/BEX2/NF-kB pathway in the modulation of the response to the hormonal drug in primary breast cancer." (PMID 36354700, 2022). "Moreover, the NGF precursor (pro-NGF) signaling pathways were related to breast cancer invasion and metastasis." (PMID 36354700, 2022).
breast cancer (continued). "Preliminary data showed that NGF and its receptors could represent a promising target for the treatment of breast cancer." (PMID 36354700, 2022). "In addition to NGF, two studies demonstrated the involvement of pro-NGF signaling pathways in breast cancer invasion and metastasis." (PMID 36354700, 2022). "Conversely, pro-NGF signaling has been related to breast cancer invasion and metastasis." (PMID 36354700, 2022). "Since the 1990s, several studies have indicated that NGF and its receptors could also play a key role in the pathogenesis of breast cancer and, consequently, could represent a new therapeutic target." (PMID 36354700, 2022). "Several examples of in vitro and in vivo evidence show that NGF is both synthesized and released by breast cancer cells, and has mitogen, antiapoptotic and angiogenic effects on these cells through the activation of different signaling cascades that involve TrkA and NGFR/p75NTR receptors." (PMID 36354700, 2022). "After providing a general overview of breast cancer and NGF signaling pathways, here we systematically review and comprehensively summarize the current experimental evidence regarding the involvement of NGF signaling pathways in breast cancer." (PMID 36354700, 2022). "Nerve growth factor (NGF) has primarily been investigated in the neurological system, but is also expressed in carcinomas, and has substantial impacts on tumor cell development and metastasis in breast cancer." (PMID 34771423, 2021). "Moreover, NGF activates breast cancer stem cells through the promotion of epithelial-mesenchymal transition and by increasing the number of symmetric divisions, which indicates that NGF is involved in the self-renewal and plasticity of cancer stem cells." (PMID 32508884, 2020). "The promotion of breast cancer angiogenesis by NGF was observed earlier." (PMID 28878143, 2017). "Interestingly, this nerve growth factor (NGF) has been demonstrated to stimulate proliferation, angiogenesis, and behaves as an anti-apoptotic factor in human breast cancer." (PMID 28420987, 2017). "A binding site next to the p75NTR DD homodimerization interface indicates that TRADD DD recruitment to p75NTR requires separation of the p75NTR DD homodimer, explaining the mechanism of NGF-dependent activation of p75NTR-TRADD-mediated antiapoptotic pathway in breast cancer cell." (PMID 28765645, 2017). "In addition to the expression of NGF, the expression of NGFR was also associated with progressive factors of breast carcinomas, such as HER2 expression, estrogen receptor negativity, and higher histologic grade." (PMID 28679437, 2017). "Its role in breast cancer is largely unknown, but the gene’s regulation of Map2, NGF and TrkA suggests an involvement in cell proliferation and renewal." (PMID 26960204, 2016). "Similarly, NGF promotes angiogenesis in breast cancer by increasing the invasion and cord formation of endothelial cells, and antibody-based neutralization inhibits this in vivo, leading NGF to be considered a candidate for therapeutic intervention." (PMID 25980435, 2015). "NGF has been reported to promote breast cancer cell proliferation and invasion." (PMID 25344915, 2014). "In addition, an algorithm for the sub-grouping of breast carcinoma patients into three sub-groups according to the expression patterns of NGF and HO1 also predicted survival of BRCA patients." (PMID 24180625, 2013). "MCF-7, T47-D, BT-20, and MDA-MB-231 breast carcinoma cells secrete NGF and express NGFR; when NGF combines with TrkA, an intracellular signal is sent via p21ras by phosphorylation and the ras-MAPK signal pathway is stimulated to influence gene transcription, translation and mediate cell growth." (PMID 22217202, 2012).
breast cancer (continued). "Combined with acceptors in the breast carcinoma cell membrane, NGF can induce proliferation and inhibit apoptosis of breast carcinoma cells via a series of cascade reactions and signal transduction, then stimulate breast carcinoma cells to produce more NGF, forming a malignant autocrine loop." (PMID 22217202, 2012). "Importantly, a xenograft model of breast cancer using MDA-MB-231 cells is responsive to anti-NGF treatments, including antibody and siRNA downregulation of NGF." (PMID 24212627, 2011). "In breast cancer cells the adaptors that link NGF/p75NTR receptor activation to NF-κB and pro-survival signaling are largely unknown." (PMID 24212627, 2011). "The precise mechanism by which NGF signaling through p75NTR protects breast cancer cells is largely unknown but functional studies have shown that it is mediated by activation of NF-κB." (PMID 24212627, 2011). "NGF is produced in an autocrine manner by breast cancer cells, and its mitogenic effects in these cells are mediated through the p42/p44 MAPK signalling pathway, since these effects can be blocked by the pharmacological inhibitor PD98059, which targets MEK1 in this pathway." (PMID 21241485, 2011). "This suggests that anti-NGF antibody therapies may prove useful in the treatment of breast cancer where overexpression of NGF is a factor." (PMID 24212627, 2011). "Although it has not been shown whether or not BEX2 interacts directly with p75NTR, it is reported to be necessary and sufficient for the anti-apoptotic function of NGF in breast cancer cells." (PMID 24212627, 2011). "The strong involvement of NGF in breast cancer angiogenesis prompted us to determine the effects of NGF on endothelial cells in terms of proliferation, migration, invasion, cord formation and permeability, as all these processes are known to be involved in tumor angiogenesis." (PMID 20569463, 2010). "Our findings provided direct evidence that NGF could be an important stimulator for breast cancer angiogenesis." (PMID 20569463, 2010). "In this study, we provided direct evidence that NGF could be an important stimulator for breast cancer angiogenesis." (PMID 20569463, 2010). "Thus, NGF, as well as the activated signaling pathways, should be taken into account for the design of future anti-angiogenic therapeutic approaches against breast cancer." (PMID 20569463, 2010). "Thus, NGF, as well as the activated signaling pathways, should be regarded as potential new targets for anti-angiogenic therapy against breast cancer." (PMID 20569463, 2010). "Importantly, neutralization of NGF with antibody against NGF reduced more than half of breast cancer cells-induced angiogenesis." (PMID 20569463, 2010). "On the other hand, NGF has been increasingly described to regulate tumor growth and progression of non-neuronal cancers including medullar thyroid carcinoma, lung, pancreatic, prostatic and breast carcinomas." (PMID 20569463, 2010). "Therefore, targeting the NGF signaling axis may be a promising treatment strategy for breast cancer patients." (PMID 40612670, 2025). "Additionally, breast cancer stem cells could be activated by NGF-induced epithelial-mesenchymal transition and the increase in the number of symmetric divisions, thereby participating in the self-renewal of cancer stem cells." (PMID 38049878, 2023). "Moreover, studies have confirmed that ProNGF, NGF and its receptors also play a role in breast cancer proliferation, ECM remodeling, angiogenesis, invasion and metastasis, and there is a correlation between the existence of nerve fibers and the expression of NGF in cancer cells." (PMID 37978384, 2023). "In addition to representing a potential new biomarker for the diagnosis of breast cancer, the analysis of NGF and its receptors could also be useful for making the differential diagnosis between various types of breast cancer." (PMID 36354700, 2022).
breast cancer (continued). "Furthermore, most of the cePathway gains in TCGA data are also found in an independent breast tumor data (GSE57297) using MACPath with the same cutoff (seeMaterials and Methods), suggesting the cePathway crosstalk between NGF and the growth factors is a common mechanism in breast cancers." (PMID 29565967, 2018). "We showed that NGF secreted by breast cancer cells could stimulate tumor angiogenesis in vivo." (PMID 20569463, 2010). "Neurotrophic factors such as NGF and BDNF are known to play roles in tumor angiogenesis in various cancers, including breast cancer and chondrosarcoma." (PMID 38375479, 2024). "Vascular endothelial growth factor (VEGF), as well as nerve growth factor (NGF), are involved in the axonogenesis of breast cancer." (PMID 36105204, 2022). "Neurotrophin 3 (NTF3) is a member of the nerve growth factor (NGF) family that is involved in the progression of various cancers, including medulloblastoma, primitive neuroectodermal brain tumors, and breast cancer." (PMID 36263167, 2022). "Together with NGF, also BDNF has been shown to play a vital role in several cancer types including breast cancer and to be highly upregulated, together with its receptors TrkB and p75." (PMID 35163823, 2022). "An oncogenic role of NGF has been supported by reports that NGF and NGFR participate in the progression of various human cancers, such as breast cancer, ovarian cancer, pancreatic cancer, oral carcinoma, and salivary gland cancer." (PMID 28679437, 2017). "The expression of NGF, HO1, and the combined NGF/HO1 expression patterns were independent indicators of poor prognosis of breast carcinomas." (PMID 28679437, 2017). "We found that NGF treatment induced CD44 binding to TrkA at the plasma membrane and subsequent activation of the p115RhoGEF/RhoA/ROCK1 pathway to stimulate breast cancer cell invasion." (PMID 25840418, 2015). "We investigated the expression and prognostic significance of the expression of NGF and HO1 in 145 cases of breast carcinoma." (PMID 24180625, 2013). "Immunohistochemical expression of NGF and HO1 was observed in 31% and 49% of breast carcinoma, respectively." (PMID 24180625, 2013). "The expression of NGF and HO1 predicted shorter overall survival of breast carcinoma by univariate and multivariate analysis." (PMID 24180625, 2013). "TrkA-induced proliferation of breast cancer cells proceeds through activation of MAP kinase signaling leading to ERK phosphorylation and an NGF-dependent decrease in cell cycle duration." (PMID 24212627, 2011). "Interestingly, the archetypal neurotrophic factor NGF has been demonstrated to stimulate proliferation, angiogenesis and behave as an anti-apoptotic factor in human breast cancer (BC) with potential for therapeutic targeting." (PMID 21767406, 2011). "This promoter is transactivated by the growth factors nerve growth factor (NGF) and epidermal growth factor (EGF) and the hormone estradiol, all of which are known to promote the proliferation and/or survival of breast cancer cells." (PMID 21241485, 2011). "As revealed by ELISA assay, NGF strongly increased the levels of secreted VEGF in both HUVEC and MDA-MB-231 breast cancer cells." (PMID 20569463, 2010). "Whilst we observed higher NGF downstream gene transcripts, the minimal Log2 fold increase of NGF and the stark downregulation NGFR persuaded us to look for other significantly upregulated genes and pathways that are biologically relevant to breast cancer metastasis." (PMID 40371393, 2025). "In addition to NGF, NGFR/p75NTR and TrkA receptors are also expressed in breast cancers cells, either at the transcriptional or protein level." (PMID 36354700, 2022). "Several evidence indicated that NGF is synthesized and released by breast cancer cells, but not from normal breast epithelial cells." (PMID 36354700, 2022). "In addition to NGF and TrkA, other researchers targeted NGFR/p75NRT signaling pathways for the treatment of breast cancer." (PMID 36354700, 2022).